RNU6-564P (RNA, U6 small nuclear 564, pseudogene)
Gene: Small nuclear RNA gene on chromosome 22 (30,421,045 to 30,421,148, forward strand). Ensembl gene ENSG00000222915.
Homologues: Orthologues: chimpanzee U6 (93% identical), macaque U6 (91% identical), pig U6 (65% identical), dog U6 (64% identical), rabbit U6 (62% identical). Paralogues in human: RNU6-1331P (80% identical), RNU6-30P (79% identical), RNU6-590P (79% identical), RNU6-797P (79% identical), RNU6-1 (78% identical), RNU6-1005P (78% identical), RNU6-1094P (78% identical), RNU6-11P (78% identical), RNU6-15P (78% identical), RNU6-188P (78% identical), RNU6-2 (78% identical), RNU6-242P (78% identical), and 1285 more.